TAF1D (TATA-box binding protein associated factor, RNA polymerase I subunit D)
Description:
Component of the transcription factor SL1/TIF-IB complex, which is involved in the assembly of the PIC (preinitiation complex) during RNA polymerase I-dependent transcription. The rate of PIC formation probably is primarily dependent on the rate of association of SL1/TIF-IB with the rDNA promoter. SL1/TIF-IB is involved in stabilization of nucleolar transcription factor 1/UBTF on rDNA. Formation of SL1/TIF-IB excludes the association of TBP with TFIID subunits.
Synonyms: TAFI41; JOSD3; MGC5306; TAF(I)41; RAFI41
Tractability: PROTAC: ubiquitination databases record sites on it.
Gene: Protein-coding gene on chromosome 11 (93,729,948 to 93,784,391, reverse strand). Ensembl gene ENSG00000166012.
Subcellular location: Nucleus
Subcellular location (Human Protein Atlas): Nucleoplasm; Centriolar satellite; Mitotic spindle; Nucleoli
Pathways (Reactome):
Gene expression (Transcription): B-WICH complex positively regulates rRNA expression; NoRC negatively regulates rRNA expression; RNA Polymerase I Promoter Escape; RNA Polymerase I Transcription Initiation; RNA Polymerase I Transcription Termination; SIRT1 negatively regulates rRNA expression
Gene Ontology:
Molecular function: identical protein binding; protein binding
Biological process: regulation of DNA-templated transcription
Cellular component: nucleoplasm; RNA polymerase transcription factor SL1 complex; nucleus
Genetic constraint (gnomAD): Loss-of-function variants: 19 observed, 23.34 expected, observed/expected ratio (o/e) 0.81, 90% interval 0.57 to 1.19. The upper end of that interval is the gene's LOEUF score, 1.19, which puts it in group 5 of 6, group 1 being the genes least tolerant of losing a copy. Missense variants: 268 observed, 305.68 expected, observed/expected ratio (o/e) 0.88, 90% interval 0.79 to 0.97. Synonymous variants: 96 observed, 100.28 expected, observed/expected ratio (o/e) 0.96, 90% interval 0.81 to 1.13.
Homologues: Orthologues: chimpanzee TAF1D (99% identical), macaque TAF1D (95% identical), guinea pig TAF1D (63% identical), pig TAF1D (61% identical), mouse Taf1d (56% identical), rat Taf1d (54% identical), tropical clawed frog taf1d (29% identical).
Diseases named in the same sentence as TAF1D in open-access papers:
TAF1D is named in the same sentence as 9 diseases in open-access papers, as found by Europe PMC text mining. Sharing a sentence is not in itself a finding about the gene and the disease. The quoted sentences say what the papers report.
mammary tumor (1 paper, 2012). "Of these, six genes (ABAT, DEPDC1, KIF2C, SMAD4A, TAF1D, and TUBB6) have been reported to be directly relevant to cancer mechanisms, such as mammary tumor progression (P = 0.046)." (PMID 23185353, 2012).
metastasis (1 paper, 2023). The spread or migration of cancer cells from one part of the body (where they first appeared) to another. "In addition, in patients with bone metastasis, patients with high tumor purity tended to have a worse prognosis, suggesting that the increase in TAF1D expression might promote the distant metastasis of OS, but further research is needed to confirm this finding." (PMID 37497412, 2023).
cancer (3 papers, 2012 to 2026). A tumor composed of atypical neoplastic, often pleomorphic cells that invade other tissues. "TAF1D was significantly upregulated in tumors, correlated with an immunosuppressive microenvironment, and promoted cancer cell proliferation by regulating cell cycle and immune-related pathways." (PMID 41969615, 2026). "Studies have shown that TAF1D is related to the poor prognosis of some patients with malignant tumors." (PMID 37497412, 2023). "In conclusion, our results indicate that TAF1D has clinically meaningful significance, particularly in OS, based on the study from pan-cancer and OS." (PMID 37497412, 2023). "In this study, we first summarized the pan-cancer expression of TAF1D and explored its clinical significance in multiple cancers." (PMID 37497412, 2023). "The results showed that the mRNA expression level of TAF1D in OS samples was higher than that in non-cancer control samples (SMD=0.57, 95% CI [0.18-0.96])." (PMID 37497412, 2023). "However, little is known about the function and role of TAF1D in other malignant tumors, especially in OS." (PMID 37497412, 2023).
tumor (2 papers, 2023 to 2026). "Compared with other clinical characteristics (sex, age, and primary tumor site), TAF1D was the only factor that indicated a poor prognosis." (PMID 37497412, 2023). "TAF1D upregulation was suggestive of worse prognosis and enhancement of tumor purity in OS patients." (PMID 37497412, 2023). "The ESTIMATE algorithm showed that the TAF1D expression level was negatively correlated with the immune score and stromal score (r=-0.319, r=-0.404) but positively correlated with tumor purity (r=0.395)." (PMID 37497412, 2023). "Critically, TAF1D exhibited significant spatial heterogeneity in expression across different samples and tissue regions, suggesting it may exert region-specific biological functions within the tumor." (PMID 41969615, 2026). "Survival analysis based on immune and stromal scores showed that patients with lower scores had a worse prognosis, which may indicate that the increase in TAF1D expression accompanied by changes in the tumor microenvironment can affect the prognosis of patients with OS." (PMID 37497412, 2023). "Additionally, the outcomes demonstrated a strong and favorable correlation between the tumor purity score and TAF1D expression (r=0.395, p<0.001), which indicated that the increase in TAF1D expression was accompanied by the enhancement of the purity of solid OS tumors." (PMID 37497412, 2023).
TAF1D also shares sentences with these, for which no sentence is quoted: gastric cancer (2 papers); cervical cancer (1); neuroblastoma (1); osteosarcoma (1); stomach cancers (1).